IGHE (immunoglobulin heavy constant epsilon)
Description:
Constant region of immunoglobulin heavy chains. Immunoglobulins, also known as antibodies, are membrane-bound or secreted glycoproteins produced by B lymphocytes. In the recognition phase of humoral immunity, the membrane-bound immunoglobulins serve as receptors which, upon binding of a specific antigen, trigger the clonal expansion and differentiation of B lymphocytes into immunoglobulins-secreting plasma cells. Secreted immunoglobulins mediate the effector phase of humoral immunity, which results in the elimination of bound antigens. The antigen binding site is formed by the variable domain of one heavy chain, together with that of its associated light chain. Thus, each immunoglobulin has two antigen binding sites with remarkable affinity for a particular antigen. The variable domains are assembled by a process called V-(D)-J rearrangement and can then be subjected to somatic hypermutations which, after exposure to antigen and selection, allow affinity maturation for a particular antigen. [Isoform 1]: Constant region of secreted IgE, also known as the Fc region of IgE antibody. Mediates IgE effector functions on myeloid and lymphoid cells primarily via two Fc receptors, the high-affinity IgE Fc receptor complex/FCER1A:MS4A2:FCGR1A and the low-affinity FCER2 receptor, which upon antigen/allergen cross-linking initiate signaling pathways that lead to immune cell activation and differentiation. Triggers the immediate hypersensitivity response to allergens as a host defense mechanism against helminth parasites, pathogenic bacteria and venom toxicity. When dysregulated, it can elicit harmful life-threatening allergic and anaphylactic reactions. Stimulates the high-affinity IgE Fc receptor complex/FCER1A:MS4A2:FCGR1A on mast cells, basophils and eosinophils leading to secretion of vasoactive amines, lipid mediators and cytokines that contribute to inflammatory response, tissue remodeling and cytotoxicity against microbes. On macrophages, cross-linking of FCER2 by IgE immune complexes induces intracellular killing of parasites through activation of L-Arginine-nitric oxide pathway. Activates macrophages to kill tumor cells via antigen-specific antibody-dependent cytotoxicity (ADCC). Triggers differentiation of quiescent M0 macrophages toward M1 state and reprograms M2 macrophages toward a proinflammatory state with antitumor functions. Stimulates FCER2 on B cells and initiates IgE-dependent antigen uptake and presentation to T cells. [Isoform 2]: Constant region of membrane-bound IgE (long mIgE), part of the B cell receptor complex (BCR). Upon antigen cross-linking triggers quick BCR signaling, ensuring survival of IgE-switched B cells and differentiation into plasma cells, thus regulating both primary and memory IgE responses. [Isoform 3]: Constant region of membrane-bound IgE (short mIgE), part of the B cell receptor complex (BCR). Upon antigen cross-linking initiates slower but sustained BCR signaling that negatively regulates mature B cell proliferation.
Synonyms: IgE
Tractability: Antibody: an approved drug acts on it; UniProt places it where antibodies can reach, with high confidence; its Gene Ontology location is reachable by antibodies, with high confidence; UniProt predicts a signal peptide or a membrane-spanning region. PROTAC: ubiquitination databases record sites on it.
Target class: Secreted protein
Gene: Immunoglobulin constant (C) gene on chromosome 14 (105,597,691 to 105,601,728, reverse strand). Ensembl gene ENSG00000211891.
Subcellular location: Secreted (Isoform 1); Cell membrane (Isoform 2); Cell membrane (Isoform 3)
Pathways (Reactome):
Immune System: FCERI mediated Ca+2 mobilization; FCERI mediated MAPK activation; FCERI mediated NF-kB activation; Fc epsilon receptor (FCERI) signaling; Interleukin-4 and Interleukin-13 signaling; Role of LAT2/NTAL/LAB on calcium mobilization
Gene Ontology:
Molecular function: immunoglobulin receptor binding; protein binding; antigen binding
Biological process: adaptive immune response; antibacterial humoral response; B cell receptor signaling pathway; complement activation, classical pathway; immune response; defense response; positive regulation of immune system process
Cellular component: extracellular region; plasma membrane; IgE immunoglobulin complex; immunoglobulin complex, circulating; immunoglobulin complex
Homologues: Orthologues: macaque IGHE (67% identical), dog IGHE (46% identical), mouse Ighe (45% identical). Paralogues in human: IGHG2 (29% identical), IGHG3 (29% identical), IGHG1 (28% identical), IGHG4 (28% identical), IGHM (25% identical), IGHA1 (22% identical), IGHA2 (22% identical), IGHD (20% identical), IGLL1 (8% identical), IGLL5 (8% identical), IGHV4-28 (7% identical), IGHV3-48 (7% identical), and 65 more.
Diseases named in the same sentence as IGHE in open-access papers:
IGHE is named in the same sentence as 828 diseases in open-access papers, as found by Europe PMC text mining. Sharing a sentence is not in itself a finding about the gene and the disease. The quoted sentences say what the papers report.
Allergy (4,145 papers, 1994 to 2026). An allergy is an immune response or reaction to substances that are usually not harmful. "(IGHE+) MBC2s may therefore represent a potential biomarker and therapeutic target for IgE‐mediated allergic diseases, which requires further investigation." (PMID 39797576, 2025).
atopic dermatitis (840 papers, 1994 to 2026). "In contrast, in atopic dermatitis, there was an increased usage of certain IGHV genes in IgE-producing cells, but there were no public IGHE clones among atopic dermatitis patients." (PMID 39596040, 2024).
eczema (430 papers, 2005 to 2026). "Despite all of our patients having elevated peripheral IgE levels and a history of eczema, the frequency of IGHE-expressing sequences was not different than in controls." (PMID 25101082, 2014).
myeloma (70 papers, 1981 to 2026). "For each patient, the following category of MM was available: light chain only, IGHA+, IGHG+, or other (including IGHM+, IGHD+, and IGHE+ rare myelomas)." (PMID 41286079, 2026).
viral infections (65 papers, 1995 to 2025). "Among the marker genes for WC syndrome, the low expression level of IGHE may be related to the inhibition of B cell activation by viral infection." (PMID 39659674, 2024).
Obesity (56 papers, 2012 to 2026). Accumulation of substantial excess body fat. "In our study, the identified association between obesity and the hypomethylated CpG site cg13074055 near the gene cluster of immunoglobulin heavy constant genes (IGHE/IGHG1/IGH) is interesting in this respect, as it suggests the expression of immunoglobulins to be potentially modified." (PMID 30397228, 2018).
breast carcinoma (30 papers, 1977 to 2025). "The roles of other IRGs in our signature in breast cancer, including IGHE, SCG2, NPR3 and FABP6, require further clarification." (PMID 33216733, 2020).
cancer (136 papers, 2007 to 2026). A tumor composed of atypical neoplastic, often pleomorphic cells that invade other tissues. "Moreover, MLNR, IGHE and RPL10L are only obtained by MVSPL, these genes are targets for cancer drugs." (PMID 31534156, 2019). "There have been no reports on IGHD and IGHE expression in cancer cells; our results showed that both IGHD and IGHE were expressed, though rarely, in myeloblasts." (PMID 35205028, 2022).
IGHE also shares sentences with these, for which no sentence is quoted: asthma (3,175 papers); food allergy (1,345); eosinophilia (985); anaphylaxis (927); allergic rhinitis (702); allergic asthma (674); infection (440); rhinitis (269); urticaria (261); dermatitis (223); airway hyperresponsiveness (217); peanut allergy (196); helminth infections (189); tumor (186); parasitic infections (166); nasal polyps (158); inflammation (132); angioedema (123); atopic asthma (109); Autoimmunity (108); respiratory allergy (108); autoimmune disease (106); Immunodeficiency (102); eosinophilic esophagitis (101); hay fever (97); allergic bronchopulmonary aspergillosis (92); hypersensitivity reactions (88); chronic spontaneous urticaria (86); wheat allergy (75); hyper-IgE syndrome (71).
A further 790 diseases each share a sentence with IGHE in 70 papers or fewer.